NR1D1 (nuclear receptor subfamily 1 group D member 1)
Description:
Transcriptional repressor which coordinates circadian rhythm and metabolic pathways in a heme-dependent manner. Integral component of the complex transcription machinery that governs circadian rhythmicity and forms a critical negative limb of the circadian clock by directly repressing the expression of core clock components BMAL1, CLOCK and CRY1. Also regulates genes involved in metabolic functions, including lipid and bile acid metabolism, adipogenesis, gluconeogenesis and the macrophage inflammatory response. Acts as a receptor for heme which stimulates its interaction with the NCOR1/HDAC3 corepressor complex, enhancing transcriptional repression. Recognizes two classes of DNA response elements within the promoter of its target genes and can bind to DNA as either monomers or homodimers, depending on the nature of the response element. Binds as a monomer to a response element composed of the consensus half-site motif 5'-[A/G]GGTCA-3' preceded by an A/T-rich 5' sequence (RevRE), or as a homodimer to a direct repeat of the core motif spaced by two nucleotides (RevDR-2). Acts as a potent competitive repressor of ROR alpha (RORA) function and regulates the levels of its ligand heme by repressing the expression of PPARGC1A, a potent inducer of heme synthesis. Regulates lipid metabolism by repressing the expression of APOC3 and by influencing the activity of sterol response element binding proteins (SREBPs); represses INSIG2 which interferes with the proteolytic activation of SREBPs which in turn govern the rhythmic expression of enzymes with key functions in sterol and fatty acid synthesis. Regulates gluconeogenesis via repression of G6PC1 and PEPCK and adipocyte differentiation via repression of PPARG. Regulates glucagon release in pancreatic alpha-cells via the AMPK-NAMPT-SIRT1 pathway and the proliferation, glucose-induced insulin secretion and expression of key lipogenic genes in pancreatic-beta cells. Positively regulates bile acid synthesis by increasing hepatic expression of CYP7A1 via repression of NR0B2 and NFIL3 which are negative regulators of CYP7A1. Modulates skeletal muscle oxidative capacity by regulating mitochondrial biogenesis and autophagy; controls mitochondrial biogenesis and respiration by interfering with the STK11-PRKAA1/2-SIRT1-PPARGC1A signaling pathway. Represses the expression of SERPINE1/PAI1, an important modulator of cardiovascular disease and the expression of inflammatory cytokines and chemokines in macrophages. Represses gene expression at a distance in macrophages by inhibiting the transcription of enhancer-derived RNAs (eRNAs). Plays a role in the circadian regulation of body temperature and negatively regulates thermogenic transcriptional programs in brown adipose tissue (BAT); imposes a circadian oscillation in BAT activity, increasing body temperature when awake and depressing thermogenesis during sleep. In concert with NR2E3, regulates transcriptional networks critical for photoreceptor development and function. In addition to its activity as a repressor, can also act as a transcriptional activator. In the ovarian granulosa cells acts as a transcriptional activator of STAR which plays a role in steroid biosynthesis. In collaboration with SP1, activates GJA1 transcription in a heme-independent manner. Represses the transcription of CYP2B10, CYP4A10 and CYP4A14 (By similarity). Represses the transcription of CES2 (By similarity). Represses and regulates the circadian expression of TSHB in a NCOR1-dependent manner (By similarity). Negatively regulates the protein stability of NR3C1 and influences the time-dependent subcellular distribution of NR3C1, thereby affecting its transcriptional regulatory activity (By similarity). Plays a critical role in the circadian control of neutrophilic inflammation in the lung; under resting, non-stress conditions, acts as a rhythmic repressor to limit inflammatory activity whereas in the presence of inflammatory triggers undergoes ubiquitin-mediated degradation thereby relieving inhibition of the inflammatory response (By similarity). Plays a key role in the circadian regulation of microglial activation and neuroinflammation; suppresses microglial activation through the NF-kappaB pathway in the central nervous system (By similarity). Plays a role in the regulation of the diurnal rhythms of lipid and protein metabolism in the skeletal muscle via transcriptional repression of genes controlling lipid and amino acid metabolism in the muscle (By similarity).
Synonyms: EAR-1; EAR1; HREV; THRAL; Rev-ErbAalpha; THRA1; REVERBA; REVERBalpha
Tractability: Small molecule: a structure with a bound ligand is known; a high-quality ligand is known; it belongs to a druggable protein family. PROTAC: UniProt records ubiquitination sites on it; ubiquitination databases record sites on it; a small molecule that binds it is known.
Target class: Nuclear hormone receptor subfamily 1 group D member 1; Nuclear receptor; Nuclear hormone receptor subfamily 1; Nuclear hormone receptor subfamily 1 group D; Transcription factor
Gene: Protein-coding gene on chromosome 17 (40,092,793 to 40,100,589, reverse strand). Ensembl gene ENSG00000126368.
Subcellular location: Nucleus; Cytoplasm; Cell projection, dendrite; Cell projection, dendritic spine
Subcellular location (Human Protein Atlas): Nuclear bodies
Pathways (Reactome):
Circadian clock: Expression of BMAL (ARNTL), CLOCK, and NPAS2; Phosphorylated BMAL1:CLOCK (ARNTL:CLOCK) activates expression of core clock genes; Phosphorylation of CLOCK, acetylation of BMAL1 (ARNTL) at target gene promoters; RORA,B,C and NR1D1 (REV-ERBA) regulate gene expression; The CRY:PER:kinase complex represses transactivation by the BMAL:CLOCK (ARNTL:CLOCK) complex
Cellular responses to stimuli: Heme signaling
Gene expression (Transcription): Nuclear Receptor transcription pathway
Metabolism: PPARA activates gene expression
Organelle biogenesis and maintenance: Transcriptional activation of mitochondrial biogenesis
Gene Ontology:
Molecular function: DNA-binding transcription repressor activity, RNA polymerase II-specific; heme binding; protein binding; RNA polymerase II cis-regulatory region sequence-specific DNA binding; RNA polymerase II transcription regulatory region sequence-specific DNA binding; sequence-specific double-stranded DNA binding; transcription cis-regulatory region binding; transcription corepressor binding; DNA-binding transcription factor activity, RNA polymerase II-specific; nuclear receptor activity; nuclear steroid receptor activity; DNA binding; DNA-binding transcription factor activity; E-box binding; sequence-specific DNA binding; zinc ion binding
Biological process: cellular response to lipopolysaccharide; cholesterol homeostasis; intracellular glucose homeostasis; negative regulation of DNA-templated transcription; negative regulation of toll-like receptor 4 signaling pathway; negative regulation of transcription by RNA polymerase II; cell differentiation; cellular response to interleukin-1; cellular response to tumor necrosis factor; circadian regulation of gene expression; circadian temperature homeostasis; glycogen biosynthetic process; hormone-mediated signaling pathway; intracellular receptor signaling pathway; negative regulation of astrocyte activation; negative regulation of canonical NF-kappaB signal transduction; negative regulation of cold-induced thermogenesis; negative regulation of inflammatory response; negative regulation of microglial cell activation; negative regulation of neuroinflammatory response; positive regulation of bile acid biosynthetic process; positive regulation of DNA-templated transcription; positive regulation of transcription by RNA polymerase II; proteasomal protein catabolic process; protein destabilization; and 9 more
Cellular component: chromatin; nuclear body; cytoplasm; dendrite; dendritic spine; nucleoplasm; nucleus
Genetic constraint (gnomAD): Loss-of-function variants: 16 observed, 51.07 expected, observed/expected ratio (o/e) 0.31, 90% interval 0.21 to 0.48. The upper end of that interval is the gene's LOEUF score, 0.48, which puts it in group 2 of 6, group 1 being the genes least tolerant of losing a copy. Missense variants: 640 observed, 848.67 expected, observed/expected ratio (o/e) 0.75, 90% interval 0.71 to 0.81. Synonymous variants: 336 observed, 341.69 expected, observed/expected ratio (o/e) 0.98, 90% interval 0.9 to 1.08.
Homologues: Orthologues: chimpanzee NR1D1 (100% identical), macaque NR1D1 (98% identical), pig NR1D1 (96% identical), rabbit NR1D1 (96% identical), dog NR1D1 (96% identical), mouse Nr1d1 (95% identical), rat Nr1d1 (95% identical), guinea pig NR1D1 (91% identical), zebrafish nr1d1 (60% identical), tropical clawed frog nr1d1 (57% identical), Caenorhabditis elegans sex-1 (20% identical), Caenorhabditis elegans nhr-23 (18% identical), and 183 more. Paralogues in human: NR1D2 (47% identical), RORA (23% identical), RORC (23% identical), PPARG (22% identical), RORB (22% identical), PPARA (21% identical), RARG (21% identical), PPARD (20% identical), RARA (20% identical), RARB (20% identical), THRB (18% identical), NR1H2 (18% identical), and 6 more.
Diseases named in the same sentence as NR1D1 in open-access papers:
NR1D1 is named in the same sentence as 178 diseases in open-access papers, as found by Europe PMC text mining. Sharing a sentence is not in itself a finding about the gene and the disease. The quoted sentences say what the papers report.
Obesity (38 papers, 2014 to 2025). Accumulation of substantial excess body fat. "To examine how loss of Nr1d1 alters adipose tissue response to diet-induced obesity, we compared directly those processes which showed significant obesity-related dysregulation in control mice." (PMID 34350828, 2021). "Mice deficient of Nr1d1 absorb more dietary fat which promotes high-fat diet induced obesity." (PMID 36746332, 2023). "Polymorphisms in the NR1D1 gene has been associated with obesity in various human populations." (PMID 32407314, 2020). "Interestingly, several studies have reported that genetic polymorphism of NR1D1 is associated with human diseases such as bipolar disorder and obesity." (PMID 31779659, 2019). "Similarly, having polymorphism in NR1D1 has been associated with the risk of developing obesity." (PMID 35267930, 2022). "This metabolic sway has positioned Nr1d1 as a tantalizing therapeutic target for metabolic disorders, including type 2 diabetes and obesity." (PMID 39472573, 2024). "Vice versa, macrophages from knockout mice had elevated CCL2 levels and enhanced tissue infiltration rates, and animals with inflammatory conditions (aging, obesity) displayed down-regulation of Reverba (Nr1d1) expression." (PMID 37833991, 2023). "Obesity resulted in overall disruption of core clock genes (i.e., Bmal1, Clock, Rev-erbα/Nr1d1, Rev-erbβ/Nr1d2, Per1, Per2, Cry1, Cry2, Dbp and Rorα) in WAT." (PMID 35198059, 2022). "Loss of NR1D1 activity in WAT did, however, significantly enhance adipose tissue expansion in response to HFD feeding; yet despite exaggerated obesity, adipocyte-specific knockout (KO) mice were spared the anticipated obesity-related pathology." (PMID 34350828, 2021). "By us and others, global deletion of Nr1d1 leads to an increase in lipogenesis, adipose tissue expansion, and an exaggerated response to diet-induced obesity." (PMID 34350828, 2021). "Given the links between circadian disruption and obesity, and the potential of NR1D1 as a pharmacological target, we now define the role of NR1D1 in dictating WAT metabolism." (PMID 34350828, 2021). "The emergence of the collagen dynamics as a direct NR1D1 target and exaggerated diet-induced obesity evident in Nr1d1-/- mice supports a role for NR1D1 in regulating adipose tissue expansion under obesogenic conditions." (PMID 34350828, 2021). "The broadening of NR1D1’s regulatory influence in response to obesity likely reflects a change to the chromatin environment in which NR1D1 operates." (PMID 34350828, 2021). "Adipose-specific deletion of Nr1d1 thus provides a unique model to explore the complex ECM responses which accompany obesity-related tissue hypertrophy and development of fibrosis." (PMID 34350828, 2021). "Genes controlling mitochondrial activity, lipogenesis, and lipid storage were relatively spared from the obesity-related down-regulation observed in control mouse tissue, and were associated with the WAT NR1D1 cistrome." (PMID 34350828, 2021). "Polymorphisms of human clock genes, such as ARNTL, circadian locomotor output cycles kaput (CLOCK), CRY2, and nuclear receptor subfamily 1, group D, member 1 (NR1D1), have been linked to obesity or some other features of metabolic syndromes." (PMID 33424933, 2020). "Interestingly, global deletion of Nr1d1 promotes lipogenesis, adipose tissue expansion, and obesity." (PMID 37961647, 2025). "Interestingly, global deletion of Nr1d1 preserves insulin sensitivity despite promoting lipogenesis, adipose tissue expansion, and obesity." (PMID 37961647, 2025). "On the contrary, the knockdown of ULK1 reverses the benefits of overexpression of NR1D1 on obesity." (PMID 38348222, 2024). "Diet-induced obesity unmasks a role for NR1D1 in the regulation of adipose expansion." (PMID 34350828, 2021). "Interestingly, we observed a strong positive correlation between body weight and daily intake of HFD in the Nr1d1-/- mice, suggesting that HFD-induced hyperphagia exacerbates weight gain and obesity in the Nr1d1-/- mice." (PMID 34350828, 2021).
Obesity (continued). "Global deletion of Nr1d1 results in obesity and increased adipose lipid synthesis." (PMID 34350828, 2021). "Importantly, NR1D1 action in adipocytes is critical to the development of obesity-related WAT pathology and insulin resistance." (PMID 34350828, 2021). "However, NR1D1 regulatory control broadens to include lipid and mitochondrial metabolism pathways under conditions of obesity." (PMID 34350828, 2021). "Moreover, upregulation of three NRs such as NR4A1, NR4A2, and NR4A3 can be used for the potential biomarkers for obesity while downregulation of NR1D1 can be used as a potential biomarker for obesity with rheumatoid arthritis as a complication." (PMID 29065888, 2017). "Thus, transcriptomic profiling correlates with phenotype in suggesting that WAT function and metabolic activity is protected from obesity-related dysfunction in the Nr1d1Flox2-6:AdipoqCre mice, and that the impact of adipose Nr1d1 deletion is dependent on system-wide metabolic state." (PMID 34350828, 2021). "Concerning the circadian clock, in the ANS/inflammation-induced obesity network constructed herein, ARNTL interacts with CLOCK, NR1D1 and CCRN4L." (PMID 39062927, 2024). "SR9009, previously reported as a small molecule ligand for NR1D1 and NR1D2, had an important role in feedback regulation of the circadian oscillator and reversing obesity." (PMID 34587364, 2021). "Together, our data show NR1D1 to be a state-dependent regulator of WAT metabolism, with its widespread repressive action only unmasked by diet-induced obesity." (PMID 34350828, 2021). "More importantly, FOXO1, CSNK1A1, NF1L3 and NR1D1 clock genes/proteins are not involved in this type of obesity." (PMID 39062927, 2024). "Here, we now uncover a role for NR1D1 in limiting the energy-buffering role of WAT, a discovery which may present therapeutic opportunity as we cope with an epidemic of human obesity." (PMID 34350828, 2021). "The circadian clock component NR1D1 (REVERBα) is considered a dominant regulator of lipid metabolism, with global Nr1d1 deletion driving dysregulation of white adipose tissue (WAT) lipogenesis and obesity." (PMID 34350828, 2021). "WAT tissue lacking Nr1d1 showed significantly increased tissue expansion, but little evidence of normal obesity-related pathology (tissue fibrosis and immune cell infiltration/inflammation)." (PMID 34350828, 2021). "Since only male mice were used in these previous studies, we do not know whether female mice lacking NR1D1 would also exhibit similar insulin-sensitive obesity phenotype." (PMID 37961647, 2025). "Similarly, genes encoding circadian clock regulators (Dbp, Nr1d1 and Nr1d2), KLF transcription factors (Klf2 and Klf6) and cell signaling molecules (Rhob and Shank3) were also upregulated in sustained obesity (cohort 2) but not in the reversion group (cohort 3)." (PMID 36400935, 2022). "Although the whole-body and adipose-specific Nr1d1 KO mice fed with HFD become markedly obese, the obesity is not accompanied by insulin resistance, adipose tissue inflammation and fibrosis." (PMID 37961647, 2025).